LEP (leptin)
Diseases named in the same sentence as LEP in open-access papers (continued):
Sharing a sentence is not in itself a finding about the gene and the disease.
Obesity (continued). "Leptin levels are increased and its negative regulators, SOCS-3 and sOb-R are decreased in obese patients with osteoarthritis: a link between obesity and osteoarthritis." (PMID 25184806, 2014). "Study the possible relationship of miR-27a, miR-27b, miR-143 and miR-145 with leptin, leptin receptors, IGF1 and IL10 is important to try to understand the changes that occur in obesity and its physiopathology." (PMID 24690978, 2014). "Most notably, in obesity both the local AT and circulating levels of inflammatory mediators, such as TNFα, IL-6, IL-1β, MCP-1, leptin and many others, are elevated, while levels of adiponectin, an anti-inflammatory adipokine, are decreased." (PMID 25360510, 2014). "The range of variations of hormones regulating human appetite, for example, leptin and ghrelin and enzymes regulating carbohydrate and fat metabolism in past and present populations may differ, thus adding to the evolutionary explanation for part of the obesity problem." (PMID 23627943, 2013). "Analysis of hormones and cytokines related to the development of obesity and hepatic steatosis showed that both MSG-containing diet groups had significantly higher levels of serum leptin and TNFα (MSG + TFA and ASP + MSG + TFA diet mice, P <0.05)." (PMID 23783067, 2013). "Studies in DIO rodents, which are widely used as a model of human obesity, have shown that the ARC is a major site of leptin resistance while some other sites within the brain remain leptin sensitive." (PMID 23527232, 2013). "Both circulating leptin and leptin receptors are needed for expression of APOM in vivo, although the exact nature of the relationship between obesity and APOM itself is not fully understood." (PMID 23544116, 2013). "Taking into consideration that serum IFN-γ has been shown to increase during obesity, it is conceivable to expect a positive relationship among TNF-α, IL-12, and leptin in our study population." (PMID 23986664, 2013). "In conclusion, the results of this study highlight novel endocrine mechanisms involving the modulation of serum leptin and CRP concentrations by which chitosan exhibits anti-obesity properties in vivo." (PMID 23342013, 2013). "A classical animal model of obesity is DIO rodents, which are unresponsive to the anorectic effect of leptin." (PMID 23527232, 2013). "Furthermore, obesity may induce a low-grade chronic inflammation that attenuates leptin signalling." (PMID 23667661, 2013). "Increased levels of leptin and reduced levels of PYY are features of obesity with peripheral insulin resistance." (PMID 25035815, 2013). "Hormone resistance to the effects of insulin, leptin, and fibroblast growth factor 21 (FGF21) has been reported in diabetes and obesity." (PMID 23409033, 2013). "The decreased bone mass with obesity may be due to increased marrow adipogenesis at the expense of osteoblastogenesis, increased osteoclastogenesis due to the upregulation of proinflammatory cytokines, excessive leptin secretion or reduced adiponectin production." (PMID 24302863, 2013). "With regard to hypertension in obesity, the present results indicated that the hypertension may be treated with the vasodilatory cardiac hormones investigated in the present study, since increased levels of leptin are correlated with the development of hypertension in obese individuals." (PMID 24137236, 2013). "Obesity is typically accompanied by elevated circulating levels of insulin, bioavailable IGF-1 and leptin, as well as a series of pro-inflammatory cytokines." (PMID 23880059, 2013). "To date, no studies have addressed whether obesity-associated endocrine factors such as leptin, regulate adipose stem cell-derived MCP-1, nor have they dissected the intracellular signaling intermediates involved in leptin-mediated MCP-1 gene expression in the stem cells." (PMID 23216800, 2012).
Obesity (continued). "Obesity leads to pro-inflammatory milieu characterised by increased levels of TNF-α, IL-6, leptin, angio-tensinogen, plasminogen activation inhibitor-1 and decreased adip-onectin levels which promote endothelial functions." (PMID 22726248, 2012). "In conclusion, we show that POMC neurons of DIO mice are resistant to STAT3 activation by leptin and that over-expression of LepRb only in POMC neurons is sufficient to potentiate the development of diet-induced obesity." (PMID 22276206, 2012). "Brain-specific deletion of SHP2 results in leptin resistance and obesity, suggesting that the LEPRb/SHP2/ERK pathway is required for a full leptin action." (PMID 22359610, 2012). "Adiponectin and leptin proved to be significantly related to TNF-α in control group and obesity was also related to TNF-α, confirming data from the literature." (PMID 22547903, 2012). "The ability of leptin to stimulate muscle AMPK is significantly impaired in high fat diet-challenged mice, suggesting muscle leptin resistance in obesity." (PMID 23115649, 2012). "Moreover, we found higher levels of leptin (an adipokine that increases in response to obesity, inhibiting appetite at brain level) in the elderly persons who were homozygote for the common allele, which may be related to the higher BMI found in these persons in our sample." (PMID 22916254, 2012). "Inflammation measured by mRNA expressions of IL-6, MMP-9, PAI-1 and leptin and protein expression of NF-κB was higher, whereas anti-inflammation measured by mRNA expressions of adiponectin and INF-γ was lower in obesity than in control and OR (all p<0.003)." (PMID 22784636, 2012). "However, it is not known whether genetic variants in genes encoding fat and obesity-associated (FTO), leptin (LEP), and leptin receptor (LEPR) associate with physical performance, and whether fitness level modifies the risk for obesity associated with these gene variants." (PMID 23284729, 2012). "Hormones such as leptin, amylin, GIP, and insulin, to which a suggested state of resistance is observed in obesity and T2D tend to decrease, favor a restored homeostasis." (PMID 22619730, 2012). "It down-regulated not only the level of blood glucose and plasma insulin but also the expression level of leptin and TNF-α mRNAs in white adipose tissue of the diabetes/obesity mouse KK-Ay." (PMID 23675258, 2012). "A close correlation between Zero-CHO diet induced obesity and elevation of blood leptin levels is seen in the fact that all of the Zero-CHO mice gained more weight and exhibited higher fasting blood leptin levels than any of the Chow fed mice." (PMID 22838969, 2012). "It is followed by the reduction of circulating mediators, including triglyceride (TG), total cholesterol, leptin, and monocyte chemotactic protein-1 (MCP-1) in obesity." (PMID 22829857, 2012). "SRLE induced prevention of pre-adipocytes differentiation, and leptin release further substantiated these findings and scientifically validates the potential application of SRLE as a therapeutic agent against obesity." (PMID 21845103, 2011). "Compared to mice fed the control diets, the expression of leptin in fat tissue and leptin-R and POMC in the hypothalamus was higher in the diet-induced obesity (DIO) mice, and the n-3 PUFAs in the diets reversed these elevated expression levels." (PMID 21609458, 2011). "However, leptin is just one factor relating to obesity that may be involved in AD pathogenesis." (PMID 22013440, 2011). "Our stratified analyses in CoLaus data suggest that sex could potentially modify the association of LEPR variants with obesity-related phenotypes, which is not surprising considering the major differences in both leptin levels and fat distribution between the sexes." (PMID 22028824, 2011). "In other studies, elevated serum levels of leptin, which acts on the hypothalamus to suppress appetite, was described in 139H scrapie in SGH despite evidence of hyperphagia and obesity." (PMID 22174765, 2011).
Obesity (continued). "However, it is still not clear whether leptin resistance is one of the causes or the consequences of obesity, or the “vicious cycle” of them might be the culprit of metabolic disorders." (PMID 21347230, 2011). "With the failure of leptin as anti-obesity therapy, recent research has focused on the gp130 receptor ligands, in particular CNTF, as potential therapeutic agents for obesity." (PMID 21937762, 2011). "However, if leptin resistance could be by-passed and genes/pathways which respond to leptin treatment could be regulated directly, new therapeutic strategies for the treatment of obesity may be possible." (PMID 20808936, 2010). "Insulin and leptin are important central signals to regulate PFC functions, and these central actions are attenuated in both obesity and diabetes." (PMID 20181219, 2010). "At this point it should be mentioned that the ob/ob model represents a model of obesity and systemic inflammation rather than a simple model of leptin deficiency with substantial diversities from human obesity that is associated with hyperleptinemia and central leptin resistance." (PMID 21040518, 2010). "Both modules show correlation with metabolic traits (leptin, BFM, BMI, HDL cholesterol, waist, and weight) and the turquoise module has been identified as a key driver of obesity traits in humans." (PMID 21179467, 2010). "Indeed, we found that the positive associations between anthropometric variables and OA were largely dependent on leptin (but not IL-6), suggesting that obesity may cause cartilage damage systemically through production of leptin in adipose tissue in females." (PMID 20482813, 2010). "These alterations seem to be due to obesity per se with its hyperinsulinaemic state as well as an interplay between PRL and leptin concentrations." (PMID 20182553, 2010). "Many obesity-related factors are responsible, including increased blood levels of insulin/IGF, IL-6, TNF-alpha, and leptin, and decreased blood levels of adiponectin." (PMID 21103795, 2010). "After this acute- term study, following only one meal, the authors rapidly suggested that because insulin and leptin (the main regulatory factors of food intake) were lower after fructose meals; they might increase caloric intake and ultimately contribute to weight gain and obesity." (PMID 21050460, 2010). "Leptin levels are 50% higher in OSAHS patients than in controls, suggesting that other factors besides obesity contribute to the elevation of leptin." (PMID 21040518, 2010). "Interestingly, apart its antiobesity effects, leptin exerts important physiological effects on the control of respiration and has been suggested to be a better predictor than percent body fat for the presence of hypercapnia in patients with obesity-hypoventilation syndrome." (PMID 20182553, 2010). "In contrast, the circulating levels of leptin and FABP-4 are also enhanced in obesity and they are primarily released by fat cells of human adipose tissue." (PMID 20508843, 2010). "This BMI-dependent effect of leptin may explain why obesity is a risk factor for OA and further supports the recent data found by Griffin and colleagues, which showed that the incidence of knee OA is not increased in extremely obese leptin-impaired signaling." (PMID 20534145, 2010). "The strong association between leptin and disease severity, coupled with the recent observation that obesity due to the impairment of leptin signaling does not cause osteoarthritis in mice, suggests that leptin itself may be a target for osteoarthritis in obese patients." (PMID 20604941, 2010). "Before the onset of obesity, young AC3−/− mice exhibit reduced physical activity, increased food consumption, and leptin insensitivity." (PMID 19750222, 2009). "Post-weaning HFD interacted with maternal obesity to increase the HOMA index and leptin:adiponectin ratio, and reduce adiponectin/g Rp fat levels (P<0.05, HFD effect and interaction with maternal obesity)." (PMID 19606226, 2009).
Obesity (continued). "Additionally, leptin may have direct functional and structural renal consequences in obesity." (PMID 20066136, 2008). "Several previous studies have reported increased plasma leptin levels in patients with OSA, however the relationship between leptin and OSA is far from being resolved mainly because the potential confounding role of obesity." (PMID 18828917, 2008). "We wanted to establish and compare levels of leptin and NPY in different obesity types in childhood, and to investigate their correlations with auxological parameters." (PMID 17721641, 2007). "The concentrations of leptin stimulating proliferation and inhibiting apoptosis in OE33 cells are consistent with serum levels in obesity." (PMID 17559672, 2007). "Here, the focus is on diet-induced obesity and MT and mammary fat pad (MFP) leptin and apoptotic signaling proteins." (PMID 18162139, 2007). "Thus, as obesity and related diseases are thought to result from resistance to leptin, it is likely that this also contributes to the cognitive deficits found in diabetics and may play a role in the impaired cognitive function associated with neurodegenerative disorders." (PMID 17618127, 2007). "The heritability of the obesity phenotypes after correction was 35% for log BMI, 28% for WHR and 36% for log plasma leptin (all p < 0.0001)." (PMID 17137505, 2006). "Unfortunately, these leptin‐induced reversals in adaptive hormone and metabolic responses are not sufficient for leptin to be used as a monotherapeutic obesity medication." (PMID 41268722, 2026). "Considering the correlation between obesity and poor clinical outcomes, these cells serve as a valuable model for investigating how obesity enhances tumor invasiveness, EMT, and metastasis and allow for comprehension of leptin’s involvement in tumor development." (PMID 41562922, 2026). "Notably, Alms1 KO rats develop hyperleptinemia as early as 7 weeks, prior to the onset of obesity, implicating ALMS1 in early leptin regulation and metabolic signaling." (PMID 41691606, 2026). "Intriguingly, one of the earliest links between obesity and cognitive deficits is demonstrated by the ob/ob mouse, where the lack of leptin leads to massive adiposity, neurodevelopment abnormalities, brain-wide myelin loss, and cognitive impairments." (PMID 40819297, 2026). "Our study suggests that the earlier puberty found in girls with obesity but not in boys cannot be explained by higher leptin levels." (PMID 41240372, 2026). "Therefore, this study aims to investigate the effects of the BPL herbal beverage on BW, LI, body fat content (BFC) percentage, lipid profiles, leptin levels, and DPP4 activity in male rats with obesity." (PMID 41510340, 2026). "Many endocrinologists note that overweight and obesity, as well as a sedentary lifestyle, may contribute to EOP in girls, most likely through the influence of the peptide hormone leptin." (PMID 41014133, 2026). "In patients with obesity, a phenomenon known as 'leptin resistance' has been suggested to explain the contradictory finding that most persons with obesity have high, rather than low, plasma leptin levels, despite their plentiful energy stores." (PMID 38778593, 2025). "The coexistence of obesity and periodontitis has been reported to increase salivary leptin levels, but it does not significantly affect adiponectin levels." (PMID 41300847, 2025). "Similarly, positive correlations between serum LEP and waist circumference (r = 0.6) and WTH ratio (r = 0.48) were observed in individuals with obesity." (PMID 40586327, 2025). "In the next section, we will explore the interaction between GPCR signaling and leptin sensitivity and highlight the therapeutic potential of combining leptin and GPCR ligands, many of which are gut peptides, neurotransmitters, and neural peptides, for obesity treatment." (PMID 41016636, 2025).
Obesity (continued). "A recent study mentioned the presence of two obesity subtypes, metabolically healthy and non-healthy, where the leptin and adiponectin levels were found to be non-significant in both obesity subtypes." (PMID 39858439, 2025). "After adjustment for potential confounders, women with obesity showed a 63% higher probability of having elevated leptin levels (Prevalence Ratio [PR] = 1.63; 95% CI: 1.32–2.02; p < 0.001) compared with those without obesity." (PMID 41439942, 2025). "For example, adipokines such as leptin and adiponectin regulate energy homeostasis and lipid metabolism, while inflammatory markers like TNF‐α and IL‐6 highlight the role of chronic inflammation in obesity." (PMID 40551726, 2025). "We summarized recent studies on the physiological interactions between GPCR and leptin signaling, offering insights into the role of GPCR signaling in enhancing leptin responsiveness, primarily focusing on GPCR- and leptin-based therapeutic strategies for the treatment of obesity." (PMID 41016636, 2025). "In obesity, STAT3 is chronically stimulated due to elevated levels of IL-6 and leptin." (PMID 41515969, 2025). "Sex-specific alterations in leptin and adiponectin were observed in patients with severe obesity but not in controls." (PMID 40943431, 2025). "This study investigated the association between gastric expression of FTO and MC4R genes and circulating levels of leptin, adiponectin, and ghrelin in individuals with and without obesity." (PMID 41423640, 2025). "Leptin resistance in obesity impacts appetite and satiety, but it does not modify the effect of leptin on the SNS." (PMID 40761303, 2025). "OA patients with sarcopenic obesity had significantly higher serum leptin levels than those with nonsarcopenic obesity." (PMID 39764565, 2025). "Leptin, which regulates appetite and energy homeostasis, is elevated in obesity but paradoxically fails to exert its anorexigenic effects due to leptin resistance." (PMID 39997062, 2025). "Of note, a recent study reported that the activation of Arc GABA non-LepR neurons triggered massive obesity and leptin resistance with intact leptin-pSTAT3 signaling, suggesting a complex neural interaction between GABAergic neurons and LepRb." (PMID 41016636, 2025). "Of these, Leptin was higher in high DAS28 samples in PsA, while PP was higher in the RA high DAS28 cohort and most of the metabolic markers were higher in the high BMI group, thus confirming their connection with obesity." (PMID 40640860, 2025). "Examining plasma adipokines and adipose health, we found that leptin was significantly increased with obesity, and tended to be lowered with BZA/CE, again primarily driven by a reduction in leptin in the obese BZA/CE-treated rats, reflecting the BZA/CE-associated reduction in adipose mass." (PMID 40048260, 2025). "Recent evidence suggests that the relationship between obesity and RKOA may also be driven by metabolic factors, such as the release of pro-inflammatory adipokines like leptin." (PMID 41013763, 2025). "uncovered the role of leptin in driving STAT3 activation and FAO in CD8+ T cells, resulting in suppressed glycolysis and effector function, consequently promoting the progression of obesity-related breast tumors." (PMID 41200178, 2025). "Multiple regression analysis identified the adiponectin/leptin ratio as an independent predictor of adipocyte geometries in both participants with and without obesity, and BW in participants without obesity." (PMID 41271970, 2025). "We have shown that mice with diet-induced obesity (DIO mice) emulate all features of human OHS, including awake hypercapnia, upper airway obstruction during sleep, sleep hypoventilation, high plasma leptin levels, and leptin resistance." (PMID 40232848, 2025). "Leptin, which regulates the appetite and metabolism, is often elevated in obesity, leading to leptin resistance, where the body no longer responds effectively to its appetite-suppressing effects." (PMID 40429763, 2025).